LGALS3 (galectin 3)
Diseases named in the same sentence as LGALS3 in open-access papers (continued):
Sharing a sentence is not in itself a finding about the gene and the disease.
diabetes (continued). "Similarly, galectin 3 (Gal-3) plasma levels were elevated in patients with type 2 diabetes, whereas the Gal-3(−/−) -induced diabetes mice model showed significantly less retinal pathology compared to controls." (PMID 35562891, 2022). "Therefore, we reviewed the clinical evidence of Galectin-3 in diabetes and its complications and discussed the potential mechanism of such relevance." (PMID 35083706, 2022). "The results of the recent investigation have shown that galectin-3 levels were significantly elevated in type 2 diabetes mellitus patients with macroalbuminuria, and higher levels of galectin-3 were found in patients with advanced kidney function (stage 4 and 5 CKD)." (PMID 35455664, 2022). "Galectin-3 also may be considered as an ideal therapeutic target, which has broad prospects in the prevention and treatment of diabetes and its complications, especially macrovascular and microvascular complications." (PMID 35083706, 2022). "Experimental optic nerve crush-induced or diabetes-associated damage to retinal ganglion cell axons in vivo is less severe in mice lacking galectin-3, and this is associated with reduced microglia/macrophage activity." (PMID 35711472, 2022). "There are also a large number of animal experiments revealing that Galectin-3 promotes the inflammation of pancreatic islet β cells and insulin target organs, leading to pancreatic β cell failure and insulin resistance, which in turn leads to diabetes." (PMID 35083706, 2022). "In diabetes, galectin-3 may mediate b-cell fibrosis through an inflammatory pathway, leading to impaired insulin secretion." (PMID 35141299, 2021). "Second, since diabetes is a chronic inflammatory disease, galectin-3 and adiponectin may act as inflammatory factors that are directly involved in insulin resistance and diabetic complications." (PMID 34096884, 2021). "Notably, the lack of Gal-3 aggravates this diabetic state and endothelial dysfunction, indicative of a positive correlation between levels of galectin-3 and insulin resistance, and of a protective role of Gal-3 in the pathogenesis of diabetes." (PMID 34079467, 2021). "In general, ablation of LGALS3 accelerates the obesity and diabetes induced by a high-fat diet." (PMID 31215398, 2019). "In fact, for a cut-off value of galectin-3 > 17.6 ng/mL, the risk of a total event was found to be three times higher (OR 2.87, p = 0.022), independent of age (OR 2.89, p = 0.022) and diabetes (OR 2.56, p = 0.045)." (PMID 30262779, 2018). "Moreover, in receiver operating characteristic analysis, a galectin-3 cut-off value of 803.55 pg/mL was found to diagnose diabetes with a sensitivity of 80.7% and a specificity of 85.5% (area under the curve = 0.912)." (PMID 26770660, 2016). "In summary, modulation of galectin-3, an emerging all-out player in metabolic disorders, deserves further scientific attention as a novel marker and therapeutic avenue for the control of metabolic disorders such as diabetes and obesity." (PMID 26770660, 2016). "However, in chronic inflammation, a condition characterizing both diabetes and obesity, galectin-3 exerts some proresolution actions limiting further tissue injury and promoting repair." (PMID 26770660, 2016). "In multivariate logistic regression analysis galectin-3 was an independent predictor of diabetes." (PMID 26770660, 2016). "Our data suggests that LGALS3 may protect against thrombus formation in diabetes by suppressing vWF expression in the endothelium." (PMID 26047815, 2015). "In the capillary endothelium of the skeletal muscle, there was less dysregulation by HFD in both strains compared to the aortic transcriptional response, suggesting a greater role for galectin-3 in the macrovascular complications of diabetes compared to microvascular disease." (PMID 26047815, 2015). "Correction for diabetes mellitus modestly mitigated the prognostic value of galectin-3." (PMID 21189092, 2011).
diabetes (continued). "Patients with higher galectin-3 more often had diabetes and atrial fibrillation (P < 0.01)." (PMID 21189092, 2011). "We show that galectin-3 has independent prognostic value, even after correction for established risk factors for poor outcome in HF, including age, sex, BNP, renal function, and diabetes mellitus." (PMID 21189092, 2011). "Previous studies have showna role for galectin-3 (Gal-3) in modulation of some AGE-mediatedresponses therefore we have also investigated the contribution of this multifunctional lectin in AGE-mediated cellretinal pathophysiology in short-term diabetes." (PMID 17641742, 2007). "Additionally, patients with diabetes had markedly elevated levels of galectin-3 in their circulation, with no associated changes related to hypertension or dyslipidemia." (PMID 40943431, 2025). "In addition, galectin-3 also played influential roles in the development of diabetes." (PMID 37626284, 2023). "Galectin-3 may affect visual function during diabetes by combining with AGEs." (PMID 35083706, 2022). "However, previous investigations have not simultaneously analyzed the effect of changes in both galectin-3 and adiponectin concentrations on the risk of diabetes and insulin sensitivity and secretion." (PMID 34096884, 2021). "In addition, the fact that galectin-3 levels can be elevated due to liver cirrhosis and pulmonary fibrosis and that sST2 can be elevated due to diabetes and hypertension may have impacted the results as well." (PMID 34362097, 2021). "Besides the neuroprotective effects of ginseng pectin, low-methoxyl citrus pectin was lately shown to protect pancreatic cells against diabetes-induced oxidative and inflammatory stress via galectin-3 (Gal-3), a β-galactoside-binding lectin involved in cellular inflammation and apoptosis." (PMID 33923111, 2021). "After adjustments for potential confounding factors, the approximate gradient associations between diabetes risk and adiponectin (negative), galectin-3 (positive) and galectin-3/adiponectin (positive) were consistently detected in both univariable and multivariable logistic regression analyses." (PMID 34096884, 2021). "Additionally, there are several reasons why the level of galectin-3/adiponectin may be superior to a single parameter in the assessment of increasing diabetes incidence." (PMID 34096884, 2021). "At day 30 after AMI, an increase in Galectin-3 plasma concentration in the median cubital vein of 1 unit, was independently associated with the 1.55-fold (p = 0.01) increased risk of LVR, six months after AMI, adjusted for age, leukocyte count, CRP and diabetes." (PMID 31511537, 2019). "Galectin-3 plasma levels in the median cubital vein on day 30, demonstrated promising predictive value for the development of negative LVR, six months later, which was identified as an independent predictor of 1.55-fold increased risk of LVR when adjusted for age, diabetes and inflammatory markers." (PMID 31511537, 2019). "A finding of note from our present study is the lack of association between plasma galectin-3 concentrations, and the presence of derangements such as arterial hypertension, diabetes, dyslipidemia, ischemic heart disease, or chronic obstructive pulmonary disease." (PMID 28471381, 2017). "Therefore, we sought to assess the role of galectin-3 in the vascular pathology of diabetes." (PMID 26047815, 2015). "We next monitored the development of spontaneous diabetes in female Galectin-3+/+ NOD and Galectin-3−/− NOD mice." (PMID 41477833, 2026). "Considering the role of galectin-3 in inflammatory and fibrotic processes, the observed relationship between LS and galectin-3 suggests that inflammatory and fibrotic processes may begin in prediabetes, like DM." (PMID 40292099, 2025). "However, the role of galectin-3 in diabetes remains unclear and further studies are needed." (PMID 40292099, 2025).
diabetes (continued). "Additionally, diabetes-associated alterations in serum biomarkers, including galectin-3, reflect ECM remodeling and contribute to diastolic dysfunction progression, highlighting the intricate interplay between galectin-3 and ECM dynamics in diabetic cardiomyopathy." (PMID 39063659, 2024). "In individualswith low ABIs, we observed a greater prevalence of diabetes mellitus, elevatedserum C-reactive protein (CRP) levels, increased galectin-3 levels, and lowerserum creatinine levels." (PMID 39076571, 2024). "The aim of this study was to evaluate whether FGF21, galectin-3 and copeptin can be used as biomarkers to identify HFpEF in patients with confirmed type 2 diabetes mellitus (DM)." (PMID 34573919, 2021). "After correcting for LV mass index, diabetes, age, gender, plasma NT-proBNP and prescribed drugs (ACE inhibitor or diuretics), plasma Galectin-3 levels still significantly correlated with E/Em levels (B = 0.195, p < 0.001)." (PMID 26582585, 2015). "Among the galectin family, galectin 3 (GAL3), GAL9, and GAL12 are the most well described members in the context of obesity, diabetes, and cancer and possess different physiological roles." (PMID 26121299, 2015). "Irrespective of malaria or diabetes status, galectin-3 correlated positively with age in the entire sample as it did in diabetic respondents who did not get malaria." (PMID 40802820, 2025). "Irrespective of diabetes status, levels of total cholesterol, low-density lipoprotein cholesterol, high-density lipoprotein cholesterol and galectin-3 were higher but triglyceride level was lower in participants with malaria." (PMID 40802820, 2025). "Although galectin-3 levels increased in malaria patients irrespective of diabetes status, its relationship with insulin resistance appears more complex than a linear fashion." (PMID 40802820, 2025). "The AS group, when compared with the group without AS, had a significantly higher prevalence of diabetes mellitus and hypertension in addition to greater fasting glucose levels, waist circumference, systolic blood pressure, and serum galectin-3 levels." (PMID 37240626, 2023). "In our study, galectin 3 is significantly higher in elderly patients with diabetes type 2 compared with patients without diabetes." (PMID 35742776, 2022). "Due to a lack of appropriate diabetes datasets, further analysis of the LPS/galectin-3-Rag GTPases/Ragulator-mTORC1 axis in the context of diabetes was not possible in the current study." (PMID 36481721, 2022). "High-sensitivity C-reactive protein, pro-collagen type III amino-terminal peptide, tissue inhibitor of metalloproteinase 1 (TIMP-1), and galectin-3 levels were higher in persons with DM than those without diabetes." (PMID 35391918, 2022). "We delved deeper into the specifics of MAM protein-protein interactions and discovered key connections between many of the altered MAM proteins in diabetes with several major protein regulators of inflammation, diabetes, and/or DR, specifically IL-1β, NFκBIA, FOXO1, SYVN1, STAT4, MAF, and LGALS3." (PMID 36139394, 2022). "Galectin-3 levels were not altered by gender, age as well as the presence of diabetes mellitus." (PMID 40179320, 2025). "To evaluate the prognostic performance of galectin-3, we compared a baseline clinical model [model 1: age, sex, LVEF, SBP, body mass index (BMI), diabetes mellitus (DM) and hsCRP] with models incorporating BNP, galectin-3 or both." (PMID 41158187, 2025). "The predictive value of galectin-3, either alone (>17.6 ng/mL) or associated with BNP (respectively >17.6 ng/mL and >500 pg/mL), remained statistically significant independent of other risk factors (age, renal function, diabetes, and LVEF)." (PMID 30262779, 2018). "The authors reported levels of 22.0 ng/mL for galectin-3 in patients with DM with HFpEF, higher than in patients without diabetes, 20.0 ng/mL." (PMID 34573919, 2021). "However, the pathophysiology of galectin-3 in diabetes is not well-known." (PMID 25302080, 2014).
diabetes (continued). "Therefore, this study aimed to investigate whether the circulating miR-1 and miR-21 expressions might be used in the diagnosis of SCAD and in acute HF with asymptomatic T2DM patients and without diabetes and to explore the relationship of these miRNAs with NT-proBNP and galectin-3." (PMID 31109008, 2019). "We created a scoring system by using diabetes mellitus status (yes = 2, no = 0) and the median levels of MMP-2 (2 vs. 0), galectin-3 (1 vs. 0) and endothelin-1 (2 vs. 0), as cut-off points." (PMID 30413105, 2018).
breast carcinoma (155 papers, 2008 to 2026). "In contrast, in a subgroup of breast cancers, a loss of galectin-3 expression was associated with EMT, indicating a differentiated role for galectin-3 in this process." (PMID 40806748, 2025). "In a recent small-molecule high-throughput screen, the μ-opioid receptor agonist loperamide was identified to cause high numbers of galectin-3 foci in MCF7 breast cancer cells, with minimal toxicity." (PMID 32286269, 2020). "Inhibition of galectin-3 leads to loss of transformed phenotypes in breast cancer and thyroid papillary carcinoma cells." (PMID 28146425, 2017). "Both galectin-3 and galectin-7 were associated with mammary tumour progression with galectin-7 being correlated to pejorative diagnosis when accumulated while reduced galectin-3 was of better prognosis." (PMID 29257082, 2017). "Canine mammary tumor cells entering the blood stream accumulate a large amount of galectin-3, which is associated with emboli formation." (PMID 27242966, 2016). "In order to investigate if oxygen deprivation would be a steering factor underlying galectin-3 expression and function in spontaneously occurring mammary tumors, a small series of metastatic CMT was examined." (PMID 26222311, 2015). "In this study we report that galectin-3 expression is associated with tumor microenvironment hypoxia in canine mammary cancer cells." (PMID 26222311, 2015). "In vitro studies using MDA-MB-435 and BT-549 breast cancer cell lines have shown a direct association between galectin-3 expression and metastatic and invasive potential." (PMID 25254965, 2014). "Mutation at the MMP9 cleavage site in galectin-3 reduces extracellular galectin-3 and also suppresses tumorigenicity of breast cancer cells." (PMID 25499743, 2014). "Recently, it was shown that extracellular galectin-3 can bind to N-cadherin in murine mammary cancer cells, and this association is mediated by Mgat5-generated N-glycans." (PMID 24982845, 2014). "We also examined the expression of two other Runx2-target genes, OPN and Galectin-3, whose expression is strongly associated with metastasis but neither has been shown to be regulated by Runx2 in metastatic breast cancer cells." (PMID 20591170, 2010). "Moreover, there have been interesting reports about the association of MUC1 sialylation with a better prognosis in breast cancer as a result of inhibiting MUC1-galectin-3 interaction." (PMID 37345016, 2023). "In addition, galectin-3 expression in most cancer cells is increased, and is associated with growth and metastases in pancreatic and breast cancer systems." (PMID 26273429, 2015). "Furthermore, soluble galectin-3 has been described to be highly secreted by breast cancer and TNBC cells and to be associated with chemotherapy resistance and immunosuppression, suggesting galectin-3 as a diagnostic marker and a potential therapeutic target in BC development and progression." (PMID 40149589, 2025). "Moreover, exogenously added galectin-3 interacts with Mgat5-modified N-linked oligosaccharides on the surface of mammary carcinoma cells and stimulates α5β1-integrin activation, enhancing fibronectin fibrillogenesis and fibronectin-dependent tumor cell spreading, and motility." (PMID 24982845, 2014). "Galectin-3 results particularly expressed in hypoxic tumor regions, where it promotes the migration and invasiveness of breast cancer cells and enhances angiogenesis and vascular mimicry." (PMID 38397187, 2024). "The relationship between galectin levels after treatment is of interest in oncology, as chemotherapy-induced galectin-3 increases have been correlated with significantly lower rates of recurrence in breast cancer." (PMID 38539500, 2024). "Looking at other galectins, galectin-3 (gal-3) has demonstrated the ability to prevent nitric oxide-induced apoptosis in human breast carcinoma cells." (PMID 38927753, 2024).